PVT1 (Pvt1 oncogene)
Diseases named in the same sentence as PVT1 in open-access papers (continued):
Sharing a sentence is not in itself a finding about the gene and the disease.
lung cancer (64 papers, 2016 to 2025). A malignant neoplasm involving the lung. "As microRNA sponges, long noncoding RNA plasmacytoma variant translocation 1 (PVT1) also plays an important role in lung cancer development." (PMID 38172925, 2024). "Next, we analyzed the GEO database (GSE30219) using lnCAR software and found that a high PVT1 expression level was also associated with poor overall survival (OS) in lung cancer patients." (PMID 36376862, 2022). "LncRNA plasmacytoma variant translocation 1 (PVT1) has been found to be frequently overexpressed in lung cancer." (PMID 36499136, 2022). "In contrast, lncRNA plasmacytoma variant translocation 1 (Pvt1) induces lung cancer progression and development, where HIF-1α regulates the expression of Pvt1 under hypoxia." (PMID 36207500, 2022). "This study assesses the association between genetic polymorphisms of PVT1 and the susceptibility to lung cancer as well as gene-environmental interaction." (PMID 31897242, 2020). "According to it was the first study and the limitations, we chose experimental design and implementation to further explore the relationship between lung cancer and PVT1 polymorphisms." (PMID 31897242, 2020). "This is the first study on the association between lncRNA PVT1 polymorphisms and the susceptibility of lung cancer." (PMID 31897242, 2020). "We found that there was a significant association between tumor size and PVT1 expression in lung cancer and HCC." (PMID 29348896, 2017). "The results shown that there was a significant association between tumor size and PVT1 expression in lung cancer (OR = 1.75, 95% CI: 1.17–2.64) and hepatocellular carcinoma (OR = 1.67, 95% CI: 1.02–2.73)." (PMID 29348896, 2017). "Another example is lncRNA PVT1 which has been demonstrated associated with multiple cancer types such as prostate cancer, lung cancer and bladder cancer." (PMID 27580177, 2016). "One notable example of the lncRNA is PVT1 (plasmacytoma variant translocation 1), which has previously been implicated in the development and progression of diabetic nephropathy as well as breast, ovarian, and lung cancer." (PMID 40722500, 2025). "Therefore, we pay our attention to investigating whether PVT1 polymorphisms may be involved in the risk of lung cancer." (PMID 31897242, 2020). "Another recent study revealed the involvement of Plasmacytoma Variant Translocation 1 (PVT1), a long non-coding RNA, in regulating autophagy through the miR-140-3p/ATG5 axis in lung cancer development." (PMID 39735666, 2025). "In the ceRNA network of lung cancer, CCNE1 interacts with SNHG1 and PVT1 via mir-497, which is known to down-regulate cyclin E1 to inhibit the growth of lung cancer cells." (PMID 38978021, 2024). "lncRNA PVT1 promoted vascular generation in lung cancer tissue, and ALKBH5 reduced m6A modification on PVT1, thereby facilitating vascular generation in lung cancer." (PMID 39220683, 2024). "Hypoxia-induced PVT1 expression can enhance cisplatin chemoresistance in lung cancer by autophagy through the PVT1/miR-140-3p/ATG5 pathway." (PMID 37255541, 2023). "In accordance with our findings, the up-regulation of PVT1 in lung cancer was found to be positively correlated with clinical tumor stage, lymph nodes and distance metastasis." (PMID 36624401, 2023). "Our study reveals that ALKBH5 promotes lung cancer progression and angiogenesis through PVT1, suggesting novel therapeutic targets for lung cancer patients." (PMID 36376862, 2022). "To verify the function of PVT1 in lung cancer cells, we also detected the expression levels of PVT1 in four lung cancer cell lines (A549, H1299, H1975, PC9) and 16HBE and found that PVT1 was also highly expressed in H1975 and A549 cells." (PMID 36376862, 2022). "Mechanistic studies showed that knockdown of ALKBH5 decreased the expression and stability of PVT1 in lung cancer cells." (PMID 36376862, 2022).
lung cancer (continued). "We next observed that PVT1 promoted the progression of lung cancer cells in vitro and in vivo and regulated the expression of VEGFA and angiogenesis in lung cancer." (PMID 36376862, 2022). "Here, our data indicate that ALKBH5 increased the expression of PVT1 by enhancing its stability and that ALKBH5 can regulate the proliferation, migration and angiogenesis of lung cancer partially through PVT1 in lung cancer cells." (PMID 36376862, 2022). "The expression of PVT1 in lung cancer and adjacent tissues, and cell lines were analyzed using the TCGA database and qPCR." (PMID 35256612, 2022). "In a previous study, knockdown of ALKBH5 and PVT1 in lung cancer cells inhibited tumor growth in mouse models." (PMID 36376862, 2022). "Tube formation assay also showed that the tube formation ability, which was suppressed by silencing ALKBH5, was partially rescued by PVT1 overexpression in lung cancer cells." (PMID 36376862, 2022). "Together, our results present a new mechanism that PVT1 is a hypoxia-related lncRNA and participates in the hypoxia-induced chemoresistance process by regulating the autophagy signaling pathway via PVT1/miR-140-3p/ATG5 axis in lung cancer." (PMID 35256612, 2022). "Our results demonstrate that ALKBH5 promotes the progression and angiogenesis of lung cancer by regulating the expression and stability of PVT1, which provides a potential prognostic and therapeutic target for lung cancer patients." (PMID 36376862, 2022). "Mechanistically, our results showed that ALKBH5 regulates the expression and RNA stability of PVT1 in lung cancer." (PMID 36376862, 2022). "Kaplan‒Meier analysis revealed that lung cancer patients with high expression levels of PVT1 had shorter overall survival (OS) than those with low expression levels of PVT1 in the TCGA database." (PMID 36376862, 2022). "Taken together, these results suggest that silencing ALKBH5 decreased the expression level of PVT1 by regulating its stability in lung cancer cells." (PMID 36376862, 2022). "Subsequently, we also investigated the functions of PVT1 using zebrafish xenograft models and found that the growth and metastasis of lung cancer cells were suppressed when PVT1 was knocked down." (PMID 36376862, 2022). "After identification of the role of PVT1 in promoting lung cancer cells’ chemoresistance ability via activating the autophagy signaling pathway." (PMID 35256612, 2022). "High expression of lncRNA PVT1 is positively correlated with clinical stage, lymph node metastasis, and distant metastasis in lung cancer patients." (PMID 36379920, 2022). "The present study aimed to analyze the regulatory relationship of hypoxia and PVT1 and the mechanism of PVT1 in the hypoxia-induced chemoresistance process of lung cancer." (PMID 35256612, 2022). "ATG5 was the key regulatory gene of the autophagy signaling pathway, and our results suggested that the hypoxia/PVT1/miR-140-3p signaling axis regulated the chemoresistance ability via regulating ATG5 expression in lung cancer." (PMID 35256612, 2022). "Our results demonstrate that ALKBH5 contributes to proliferation, migration and angiogenesis through PVT1 in lung cancer, thus providing a potential antitumor therapeutic target for lung cancer patients." (PMID 36376862, 2022). "All the results demonstrated that the highly expressed PVT1 affected the sensitivity of lung cancer to cisplatin in vitro and in vivo." (PMID 35256612, 2022). "A public database was used to analyze the expression and overall survival of ALKBH5 and PVT1 in lung cancer patients." (PMID 36376862, 2022). "The role of PVT1 in the chemoresistance of lung cancer cells under hypoxia or normoxia conditions was analyzed with CCK-8 assay." (PMID 35256612, 2022). "PVT1 participated in hypoxia-induced chemoresistance of lung cancer cells by promoting the autophagy signaling pathway via the PVT1/miR-140-3p/ATG5 axis." (PMID 35256612, 2022).
lung cancer (continued). "Through literature retrieval and mining technology, we obtained susceptibility genes corresponding to the four serological indexes associated with lung cancer as follows: NSE, LATS1; CA153, BCAR4; CYFRA21-1, YAP; and CA125, PVT1." (PMID 34630106, 2021). "Yang et al18 showed that the lung cancer tissues and cells exhibit increased lncRNA PVT1 expression, which is closely correlated with the pathological stage and lymph node involvement in patients with lung cancer." (PMID 32960485, 2021). "We obtained susceptibility genes corresponding to the four serological indexes associated with lung cancer as follows: NSE, LATS1; CA153, BCAR4; CYFRA21-1, YAP; and CA125, PVT1." (PMID 34630106, 2021). "Transcription factor YY1 plays a role in promoting transcription by combining with the promoter region of lncRNA PVT1, increases the proliferation of lung cancer cells, and inhibites their apoptosis." (PMID 33542193, 2021). "Up to present, PVT1 was reported to play important roles in the development of lung cancer and NSCLC, by some researchers." (PMID 31897242, 2020). "For example, lncRNA PVT1 was expressed at high levels in lung cancer cells, which promoted proliferation of non-small cell lung cancer cells by regulating LATS2 expression." (PMID 30925672, 2019). "PVT1 is another lncRNA, which is upregulated in lung cancer and plays a crucial role in lung cancer progression." (PMID 31379917, 2019). "Increasing reports showed that many lncRNAs including RMRP, PVT1, HOTAIR, HIT, and TUG1 showed disease-associated dysregulation in lung cancer." (PMID 30154938, 2018). "Stratified analysis by type of cancer indicated a significant relationship between PVT1 overexpression and high incidence of lymph node metastasis in lung cancer (OR = 4.42, 95% CI 2.11–9.27)." (PMID 29348896, 2017). "Several known lung cancer-associated lncRNAs, such as HOTAIR, GAS5, PVT1, and UCA1 were found in this top list which further supported the power of this analysis." (PMID 26862852, 2016). "Additionally, PVT1 has been recognized as an essential element in the complex landscape of cancer pathogenesis, especially in lung cancer." (PMID 41080754, 2025). "To determine whether ALKBH5 mediates the m6A modification of PVT1 in lung cancer cells, we carried out RNA immunoprecipitation (RIP) assays which revealed that ALKBH5 bounded directly to PVT1 in A549 cells." (PMID 36376862, 2022). "It remains unclear whether PVT1 promotes the chemoresistance ability of lung cancer under hypoxia conditions." (PMID 35256612, 2022). "The research also suggested that hypoxia enhanced the expression of PVT1 in lung cancer cells." (PMID 35256612, 2022). "PVT1 is highly expressed in lung cancer and cell lines, and the expression of PVT1 is regulated by HIF-1α, and the luciferase reporter assay and CHIP-qPCR analysis indicated that HIF-1α could bind to the promoter region of PVT1 and regulate PVT1 expression." (PMID 35256612, 2022). "Finally, rescue experiments revealed that ALKBH5 regulated the proliferation, migration and angiogenesis of lung cancer cells, partially through PVT1." (PMID 36376862, 2022). "We then analyzed which factor induces PVT1 expression in lung cancer." (PMID 35256612, 2022). "The two studies also showed YTHDF2 could recognize m6A-modified sites of lncRNA KCNQ1OT1 or PVT1 and regulate their stability, but whether ALKBH5 regulates the stability of PVT1 via YTHDF2 in lung cancer cells remains to be examined further." (PMID 36376862, 2022). "PVT1 is highly expressed in lung cancer tissue and the cancer cell lines." (PMID 35256612, 2022). "Our results provide a better understanding of hypoxia-induced chemoresistance and the hypoxia/PVT1/miR-140-3p/ATG5/autophagy signaling axis may be a novel treatment target for lung cancer." (PMID 35256612, 2022). "Our results demonstrated that PVT1 was highly expressed in lung cancer tissue and cell lines." (PMID 35256612, 2022).
lung cancer (continued). "We next investigated the roles of PVT1 in lung cancer angiogenesis." (PMID 36376862, 2022). "Furthermore, we identified that the mechanism by which ALKBH5 regulates proliferation, migration and angiogenesis includes the regulation of the stability of PVT1 in lung cancer cells." (PMID 36376862, 2022). "Pvt1 activates Myeloid-derived suppressor cells (MDSCs) which have a role in blocking T-cell-induced antitumor responses resulting in induction of immunosuppression activity in lung carcinoma." (PMID 36207500, 2022). "We also noticed that lncRNA PVT1 expression in lung cancer cells could be regulated by a transcription factor YY1." (PMID 34805417, 2021). "However, the oncogene lncRNA plasmacytoma variant translocation 1 (PVT1), XIST, and MALAT1 have all been demonstrated to promote autophagy through LC3 cleavage, which can enhance the chemoresistance of lung cancer cells." (PMID 33931980, 2021). "Wang and colleagues confirmed that PVT1 was overexpressed in the hypoxic lung cancer cells and it was involved in cell growth and proliferation, demonstrating that PVT1 knockdown could significantly suppress lung cancer cell proliferation in vitro." (PMID 33673376, 2021). "Consequently, we conducted our case-control study and stratified lung cancer into NSCLC, lung adenocarcinoma and lung squamous cell carcinoma to further analysis the association between PVT1 polymorphisms and lung cancer." (PMID 31897242, 2020). "Thus, we subsequently conducted a meta-analysis to assess the relationships between LINC01133, UCA1 and PVT-1 expression and OS in lung cancer patients." (PMID 29137343, 2017). "Patients with high levels of lncRNA PVT1 have a significantly lower overall survival rate than those with low levels, and lncRNA PVT1 may represent a new biomarker and possible therapeutic target for patients with lung cancer." (PMID 36379920, 2022). "Finally, we investigated the functional mechanism between ALKBH5 and PVT1 in lung cancer cells." (PMID 36376862, 2022). "Our results showed that silencing ALKBH5 and PVT1 suppressed the proliferation of lung cancer cells in zebrafish xenografts, which is consistent with the results of mouse models, indicating that zebrafish xenografts could be a reliable model for human cancer research." (PMID 36376862, 2022). "MALAT1 and PVT1 levels were mostly higher in AA lung cancer patients, while RMRP was notably elevated in WA lung cancer patients (all p < 0.05)." (PMID 38791954, 2024). "For AAs, the most accurate prediction for lung cancer was achieved by combining three lncRNAs (MALAT1, PVT1, and SNHG1) with smoking pack-years." (PMID 38791954, 2024). "Eventually, a total of four genes including, CD151, MMP1, PVT1, and SKP2 genes were selected as reference genes based on their known functions in lung cancer progression and lymph node metastasis which have been pointed out in the found articles." (PMID 37185598, 2023). "We first analyzed the correlation of expression between PVT1 and VEGFA using the GEPIA website and found that they were significantly correlated with each other in lung cancer tissues." (PMID 36376862, 2022). "Overexpression of PVT1 partially restored the proliferation, migration and angiogenesis suppressed by ALKBH5 knockdown in lung cancer." (PMID 36376862, 2022). "Furthermore, the expression and stability of lncRNA PVT1 (long noncoding RNA plasmacytoma variant translocation 1) were regulated by ALKBH5, and PVT1 overexpression partially restored the proliferation, migration and angiogenesis of lung cancer cells, which was suppressed by ALKBH5 knockdown." (PMID 36376862, 2022). "PVT1 also increased the expression of MMP‐2 and MMP‐9 to promote EMT, which ultimately made lung cancer cells radioresistant." (PMID 33931980, 2021). "The copy number of PVT1 is demonstrated to be significantly increased in patients with multiple cancers, such as renal cell carcinoma (RCC), lung cancer, esophageal cancer, and so on." (PMID 34592894, 2021).
lung cancer (continued). "Of these, 57 (25%) underwent alternative polyadenylation in lung cancer, including DLEU1, LINC01138, and PVT1." (PMID 34556645, 2021). "The top 5 long non-coding RNAs that use the IPCARF algorithm to predict lung cancer are: GAS5,XIST,CDKN2B-AS1, PVT1 and HOTAIR." (PMID 33794766, 2021). "Compared with adjacent tissues, PVT1, HCG18, EXOC3-AS1 were upregulated in most lung cancer tissues." (PMID 28938549, 2017). "Recent studies have suggested that many lncRNAs are of great importance in lung cancer, such as HOTAIR, NEAT1 and PVT1." (PMID 28981099, 2017). "Meanwhile, alterations of PVT1 and NEAT1 will reduce the overall survival and disease free survival in lung cancer." (PMID 28938549, 2017). "A recent publication found ALKBH5 can facilitate the advancement and angiogenesis of lung cancer by modulating the stability of the long non-coding RNA (LncRNA) PVT132, and PVT1 was also reported highly upregulated in GBM tissues and cells, and involved in GBM malignant progression." (PMID 38221546, 2024). "AA lung cancer patients show elevated MALAT1 and PVT1 levels compared to cancer-free smokers." (PMID 38791954, 2024). "LncRNA PVT1 may promote cell apoptosis through the miR-424-5p/PVT1/CARM1 signaling pathway, thereby enhancing the radiosensitivity of lung cancer cells." (PMID 37056929, 2023). "A zebrafish lung cancer xenograft model was used to verify the function of ALKBH5 and PVT1 in vivo." (PMID 36376862, 2022). "The overexpression of PVT1 could upregulate expression levels of SLC7A5 mRNA and induce the proliferation of lung cancer cells by acting as a sponge for miR-126." (PMID 36499136, 2022). "Thus, we examined the relationship between ALKBH5 and PVT1 in lung cancer and found that knockdown of ALKBH5 decreased the expression levels of PVT1 in A549 and H1975 cells." (PMID 36376862, 2022). "LncRNA PVT1, SBF2‐AS1, and nuclear paraspeckle assembly transcript 1 (NEAT1) are also involved in this regulatory network of lncRNA‐microRNA‐mRNA and can affect the radiosensitivity of lung cancer cells." (PMID 33931980, 2021). "Several characterized cancer-associated lncRNAs were identified, such as PVT1, TINCR, and GAS5; while the well-known lung cancer-associated lncRNA, MALAT1 was not included." (PMID 26918601, 2016). "Our study is the first to combine PVT1 and miR-143–3p within a ceRNA axis that converges on CDK1, offering a systems-level viewpoint that unifies non-coding RNA regulation with a central cell cycle kinase, even though both have been previously connected to lung cancer." (PMID 41080754, 2025). "However, a mouse model for studying the metastatic roles of ALKBH5 and PVT1 in lung cancer is lacking." (PMID 36376862, 2022). "Studies now believe that PVT1 can stimulate the angiogenesis of non-small cell lung cancer (NSCLC) by sponging miRNA to promote the VEGF-type transduction pathway, thereby promoting lung cancer progression, and PVT1 can also promote the growth and metastasis of NSCLC through the Wnt/β-catenin axis." (PMID 33585468, 2020).